BHLHA15 (basic helix-loop-helix family member a15)
Description:
Plays a role in controlling the transcriptional activity of MYOD1, ensuring that expanding myoblast populations remain undifferentiated. Repression may occur through muscle-specific E-box occupancy by homodimers. May also negatively regulate bHLH-mediated transcription through an N-terminal repressor domain. Serves as a key regulator of acinar cell function, stability, and identity. Also required for normal organelle localization in exocrine cells and for mitochondrial calcium ion transport. May function as a unique regulator of gene expression in several different embryonic and postnatal cell lineages. Binds to the E-box consensus sequence 5'-CANNTG-3' (By similarity).
Synonyms: bHLHb8; MIST1
Tractability: PROTAC: ubiquitination databases record sites on it.
Gene: Protein-coding gene on chromosome 7 (98,211,439 to 98,215,457, forward strand). Ensembl gene ENSG00000180535.
Subcellular location: Nucleus
Subcellular location (Human Protein Atlas): Golgi apparatus; Nucleoplasm
Pathways (Reactome):
Developmental Biology: Developmental Lineage of Pancreatic Acinar Cells
Gene Ontology:
Molecular function: protein binding; sequence-specific double-stranded DNA binding; DNA-binding transcription factor activity, RNA polymerase II-specific; E-box binding; DNA binding; DNA-binding transcription activator activity, RNA polymerase II-specific; identical protein binding; protein dimerization activity; RNA polymerase II transcription regulatory region sequence-specific DNA binding
Biological process: axon development; cellular response to glucose starvation; endoplasmic reticulum unfolded protein response; negative regulation of myotube differentiation; positive regulation of transcription by RNA polymerase II; sensory organ development
Cellular component: chromatin; nucleus
Genetic constraint (gnomAD): Loss-of-function variants: 7 observed, 7.74 expected, observed/expected ratio (o/e) 0.9, 90% interval 0.51 to 1.64. That is too few expected variants to judge how well the gene tolerates losing a copy. Missense variants: 289 observed, 232.98 expected, observed/expected ratio (o/e) 1.24, 90% interval 1.13 to 1.37. Synonymous variants: 140 observed, 107.08 expected, observed/expected ratio (o/e) 1.31, 90% interval 1.14 to 1.5.
Homologues: Orthologues: chimpanzee BHLHA15 (99% identical), mouse Bhlha15 (82% identical), pig BHLHA15 (81% identical), guinea pig BHLHA15 (80% identical), rat Bhlha15 (80% identical), rabbit BHLHA15 (73% identical), tropical clawed frog bhlha15 (48% identical), zebrafish bhlha15 (42% identical), Drosophila melanogaster dimm (41% identical). Paralogues in human: NEUROD4 (30% identical), NEUROD2 (30% identical), NEUROD1 (29% identical), NEUROD6 (29% identical), NEUROG1 (26% identical), NEUROG2 (26% identical), BHLHE22 (22% identical), NEUROG3 (22% identical), ATOH1 (22% identical), ATOH7 (22% identical), OLIG3 (21% identical), OLIG2 (21% identical), and 3 more.
Diseases named in the same sentence as BHLHA15 in open-access papers:
BHLHA15 is named in the same sentence as 49 diseases in open-access papers, as found by Europe PMC text mining. Sharing a sentence is not in itself a finding about the gene and the disease. The quoted sentences say what the papers report.
pancreatitis (13 papers, 2011 to 2023). Inflammation of the pancreas. "Bhlha15 knockout mice promote pancreatitis by epigenetic reprogramming of genes via histone modification." (PMID 34809720, 2021). "Mice lacking the transcription factor Bhlha15 exhibited an altered stress response, increased sensitivity to caerulein-induced pancreatitis, altered cell proliferation." (PMID 36273194, 2022).
pancreatic cancer (9 papers, 2014 to 2022). "A class of basic helix protein 15 (BHLHA15) plays a tumor inhibitory role in mice, and is down regulated in pancreatic cancer cell lines, and is related to differentiation." (PMID 35568702, 2022). "BHLHA15 expression is downregulated in pancreatic cancer tissues, whereas overexpression of BHLHA15 inhibits the proliferation, migration, and invasion of human pancreatic cancer cells." (PMID 36147499, 2022). "Thus, we identified a strong repression of selected differentiation genes, such as Ptf1a, Rbpjl, Mist1 (Bhlha15, basic helix-loop-helix family, member a15) and Amy (alpha-Amylase) in 3D-ADMs and pancreatic tumor cells." (PMID 26716510, 2016).
maturity-onset diabetes (2 papers, 2022 to 2025). "The evaluation of changes in expression of the same genes in humans with type 2 diabetes or prediabetes compared with non-diabetics show consistently upregulated BHLHA15 (MIST1), a potent endoplasmic reticulum (ER) stress-inducible transcriptional regulator upregulated by beta cell Ca2+ overload." (PMID 34554282, 2022).
diabetes (1 paper, 2018). "BHLHA15 knockout mice have decreased expression of Glut2 in pancreatic β-cells and age-related impairment in glucose clearance, suggesting that its down-regulation could contribute to the development of diabetes in these patients." (PMID 29439679, 2018).
epilepsy (1 paper, 2023). A brain disorder characterized by episodes of abnormally increased neuronal discharge resulting in transient episodes of sensory or motor neurological dysfunction, or psychic dysfunction. "The other two genes associated with TSC and epilepsy were BHLHA15, a basic-loop-helix transcription factor and CARD16, an inhibitor of apoptosis; both of uncertain relevance to TSC pathogenesis." (PMID 37996417, 2023).
esophageal adenocarcinoma (1 paper, 2021). A malignant tumor with glandular differentiation arising predominantly from Barrett mucosa in the lower third of the esophagus. "The combination of SLC26A9 with AP002478.1, BHLHA15, FFAR2, IGFBP1, KCTD8, and PHYHD1 was also identified as a gene signature for personalized prognosis prediction and targeted therapy of esophageal adenocarcinoma." (PMID 35008199, 2021).
MODY (1 paper, 2018). "Interestingly, 3 genes involved in MODY signaling pathway, including Bhlha15, Mnx1 and Nkx6.1, changed." (PMID 29879176, 2018).
myeloma (1 paper, 2022). "For example, BHLHA15/MIST1 identified in myeloma has been reported as a plasmacytic differentiation marker and potentially controlled transcriptional network with stage-specific overexpression during plasma cells differentiation." (PMID 36528241, 2022).
tumor (15 papers, 2015 to 2026). "Other groups developed similar models with mutations in Ink4/Arf (also known as Cdkn2a), Muc1, Mist1 (also known as Bhlha15), Smad4 and Tgfbr2 tumor suppressors." (PMID 29903803, 2018).
cancer (12 papers, 2014 to 2026). A tumor composed of atypical neoplastic, often pleomorphic cells that invade other tissues. "BHLHA15 (also known as Mist1), a basic helix-loop-helix transcription factor, can give rise to cancers." (PMID 34234806, 2021). "Top up-regulated genes related to cancer were: (i) IL-20, CLK1, SORBS2, ERG1, PIM1, SNORD3A for normal FHC cells and (ii) TSLP, BHLHA15, LAMP3, ZNF27B, KRT17, ATF3 for cancerous HT29 cells." (PMID 38033043, 2023).
BHLHA15 also shares sentences with these, for which no sentence is quoted: gastric cancer (9 papers); gastric neoplasm (4); melanoma (3); adenocarcinoma (2); colitis (2); Gastric Metaplasia (2); gastrointestinal disease (2); Helicobacter infection (2); infection (2); liver disease (2); pancreatic ductal adenocarcinoma (2); prostate carcinoma (2); acinic cell carcinoma of (1); acute pancreatitis (1); adenoma (1); alcoholic pancreatitis (1); alcoholic steatohepatitis (1); atrophic gastritis (1); breast carcinoma (1); carcinoma in situ (1); chronic pancreatitis (1); connective tissue disorder (1); COVID-19 (1); dry eye (1); dysplasia (1); fatty liver disease (1); fibrosis (1); gastric adenocarcinoma (1); ileitis (1); intraepithelial neoplasia (1).
A further 9 diseases each share a sentence with BHLHA15 in 1 paper.